CA4 (carbonic anhydrase 4)
Diseases named in the same sentence as CA4 in open-access papers (continued):
Sharing a sentence is not in itself a finding about the gene and the disease.
brain tumor (2 papers, 2016 to 2019). "We further tested CA4 in the brain tumor microenvironment and found that CA4 had a high efficacy in inhibiting tumor growth ex vivo." (PMID 26831010, 2016).
cardiac hypertrophy (2 papers, 2013 to 2026). "CA4 and HIF‐1α are associated with cardiac hypertrophy, whereas SIRT2 is negatively associated with hypertrophic cardiac disease." (PMID 40898929, 2026).
cholangiocarcinoma (2 papers, 2020 to 2021). A carcinoma that arises from the intrahepatic biliary tree (intrahepatic cholangiocarcinoma) or from the junction, or adjacent to the junction, of the right and left hepatic ducts (hilar cholangiocarcinoma). "Nevertheless, CA4 mRNA expressions were found significantly higher in cholangiocarcinoma (CHOL) and liver hepatocellular carcinoma (LIHC) compared to the corresponding normal tissues (**p < 0.01, ***p < 0.001)." (PMID 32922550, 2020).
retinal disease (2 papers, 2020 to 2024). "CA4 mutations have been found to be associated with retinal diseases and photoreceptor degeneration, and also found to be downregulated in various tumors." (PMID 38428408, 2024).
Sepsis (2 papers, 2023 to 2025). Sepsis is defined as life-threatening organ dysfunction caused by a dysregulated host response to infection. "Logistic regression was used to assess the likelihood of sepsis based on CA4, OLAH, and VNN1." (PMID 37608823, 2023). "In addition, carbonic anhydrases IV and II (CA4 and CA2), which produce H2CO3, were upregulated in sepsis." (PMID 40699834, 2025).
stomach adenocarcinoma (2 papers, 2020 to 2023). "CA4 was either down-regulated or expressed at very low levels across all cancer types, except for stomach adenocarcinoma (STAD) where the expression slightly increased but remained at a very low level." (PMID 35787947, 2023).
acute lymphoblastic leukemia (1 paper, 2015). Leukemia with an acute onset, characterized by the presence of lymphoblasts in the bone marrow and the peripheral blood. "In acute lymphoblastic leukemia (ALL), levels of HIF-1α, GLUT1, GLUT3, CA4, and glyceraldehyde-3-phosphate dehydrogenase (GAPDH) were significantly greater in leukemic cells compared to healthy blood cells." (PMID 26437434, 2015).
age-related macular degeneration (1 paper, 2025). Age-related loss of vision in the central portion of the retina (macula), secondary to retinal degeneration. "The Ca4 gene is a specific marker of choroidal capillary-restricted endothelial cells, and it impacts the treatment of pigmented retinitis and age-related macular degeneration." (PMID 40271076, 2025).
Anxiety (1 paper, 2019). Intense feelings of nervousness, tension, or panic often arise in response to interpersonal stresses. "The connection of D-ribose with CA4/DG neuronal death and anxiety and the underlying mechanism need further investigation." (PMID 31307014, 2019).
anxiety disorder (1 paper, 2022). A category of psychiatric disorders which are characterized by anxious feelings or fear often accompanied by physical symptoms associated with anxiety. "Research into nervous system diseases has identified CA4 as a novel therapeutic target for anxiety disorder and posttraumatic stress disorder." (PMID 36034287, 2022).
bladder cancer (1 paper, 2022). "In addition, CA-4 could inhibit microtubule polymerization, cell migration and tumor growth in bladder cancer, further suggesting the antitumor activities of CA-4." (PMID 35890172, 2022).
cervix carcinoma (1 paper, 2024). "In general, the human cervix carcinoma HeLa cells were more sensitive to both these two series of compounds as compared with the other four cell lines, with derivatives 6g and 11a being 10-fold more potent than CA-4, while compounds 6a, 6c, and 6f had nearly equivalent activity to CA-4." (PMID 39062759, 2024).
chronic myelogenous leukaemia (1 paper, 2020). "They incorporated the aryl substitution pattern of CA-4 into their chalcones to obtain several compounds with potent in vitro antiproliferative activity at nanomolar concentrations against human chronic myelogenous leukaemia K562 cell lines, superseding the activity of CA-4." (PMID 31947889, 2020).
chronic obstructive pulmonary disease (1 paper, 2025). A chronic and progressive lung disorder characterized by the loss of elasticity of the bronchial tree and the air sacs, destruction of the air sacs wall, thickening of the bronchial wall, and mucous accumulation in the bronchial tree. "In adulthood, however, increased CA4 expression has recently been linked to dystrophic calcification of the ECM resulting in stiffening of airway cartilage in chronic obstructive pulmonary disease (COPD)." (PMID 41078088, 2025).
disc degeneration (1 paper, 2024). "This extends the utility of contrast‐enhanced micro‐CT with CA4+ in the study of disc degeneration beyond prior work assessing sGAG content." (PMID 38222801, 2024).
endothelial dysfunction (1 paper, 2025). In vascular diseases, endothelial dysfunction is a systemic pathological state of the endothelium (the inner lining of blood vessels) and can be broadly defined as an imbalance between vasodilating and vasoconstricting substances produced by (or acting on) the endothelium. "The set includes genes such as CLDN18, NOS2, SLC4A1, CA4, COL17A1, and SP7, many of which have been implicated in vascular inflammation, endothelial dysfunction, and extracellular matrix remodelling." (PMID 41226477, 2025).
foot and mouth disease (1 paper, 2021). A viral infectious disease that results in infection in cattle and swine, has material basis in foot-and-mouth disease virus, which is transmitted by contaminated fomites, or transmitted by ingestion of food contaminated with infected meat or animal products. "The EV-A types identified included coxsackievirus A2 (CA2), CA4, and EV71, typically associated with hand, foot and mouth diseases." (PMID 34301271, 2021).
germ cell tumor (1 paper, 2021). A benign or malignant, gonadal or extragonadal neoplasm that originates from germ cells. "In addition to the specific CA-4 resistance of HT29 cells, the cisplatin-resistant germ cell tumor cell line 1411HP generally showed a lower sensitivity to CA-4 and the imidazoles when compared with its cisplatin-sensitive counterpart cell line H12.1 but also when compared with the other cell lines." (PMID 34884888, 2021).
herpangina (1 paper, 2014). "In this study, we found CA4 usually caused herpangina with high grade fever, leukocytosis and higher CRP but rarely caused complications." (PMID 24504149, 2014). "Patients who were infected by CA4 usually had oral ulcers (80.6%), which is a typical symptom of herpangina, and decreased oral intake (86.4%)." (PMID 24504149, 2014).
legionellosis (1 paper, 2020). Any disease caused by Legionella bacteria. "The results revealed three up-regulated genes (SEC22B, CXCL2, and CYCS) and two down-regulated genes (CA3, CA4) were significantly involved in Legionellosis and nitrogen metabolism pathways, respectively." (PMID 32174961, 2020).
metastatic prostate carcinoma (1 paper, 2009). A carcinoma that arises from the prostate gland and has spread to other anatomic sites. "Taking our IHC data of PDIA3 into account, PDIA3 protein concentration decreases significantly in CA5 compared to CA4 tissues and expression data comparing localized with metastatic prostate cancer showed a down-regulation of PDIA3." (PMID 20035634, 2009).
mouth disease (1 paper, 2011). "Complex recombinant forms of CA16-related viruses involving multiple human enteroviruses, subgroup A (CA4, CA16, and enterovirus 71), are prevalent among patients with hand, foot, and mouth disease." (PMID 21801645, 2011).
osteosarcoma (1 paper, 2023). A usually aggressive malignant bone-forming mesenchymal neoplasm, predominantly affecting adolescents and young adults. "During the peritumoral treatment of K7 osteosarcoma-bearing BALB/c mice, the CA4/PTX co-loaded hydrogel exhibited significantly higher antitumor efficacy compared with free CA4/PTX mixed solution and the hydrogel loaded with CA4 or DTX-encapsulating microspheres." (PMID 37265604, 2023).
Parkinson disease (1 paper, 2025). A progressive degenerative disorder of the central nervous system characterized by loss of dopamine producing neurons in the substantia nigra and the presence of Lewy bodies in the substantia nigra and locus coeruleus. "Collectively, our study demonstrates that CA4 plays a pivotal role in Parkinson’s disease pathogenesis." (PMID 41323222, 2025).
pulmonary disorder (1 paper, 2022). "Based on pathway enrichment analysis, genes altered in BPD blood cells were mainly enriched in cell cycle regulation and arrest (e.g., PPP2CA, RBL2, CENPU, CCNY, CDK6) and pulmonary disorder and developmental disorders (e.g., AGER, ITGA6, CA4, BACH2, IGFBP2, BMPR2, SKI, DAB2)." (PMID 35484630, 2022).
salpingitis (1 paper, 2023). Acute or chronic inflammation of the fallopian tube. "In this study, HK2 and MOGAT1 were upregulated and CA4, CNTN3, and ACAN were downregulated in the CN-LPS group, suggesting that LPS-induced salpingitis caused abnormal lipid and sugar metabolism and altered the acid–base balance of the internal environment, degrading the extracellular matrix." (PMID 37978561, 2023).
tumor (93 papers, 2001 to 2025). "A further cluster of immature endothelial cells (Endo Imm), defined by expression of PLVAP, VWA1, and CA4, was identified and has been implicated in poor tumor prognosis." (PMID 40161579, 2025). "Research demonstrated that upon irradiation with a 690 nm laser, the prodrug generates 1O2, causing localized tumor damage while simultaneously releasing CA-4." (PMID 39144632, 2024). "CA4 is a tubulin-binding agent that destroys the vasculature by selectively targeting and destroying established tumor vascular ECs, causing tumor vascular blockage and leading to the ischemic necrosis of tumor tissue." (PMID 37111692, 2023). "CA4 can enhance the expression of MMP9 in tumor tissue by destroying immature tumor blood vessels and causing a hypoxic microenvironment that significantly promotes the release of DOX prodrugs." (PMID 37111692, 2023). "CA4 showed higher cytotoxicity than Pt(IV)-CA4 conjugates in vitro, while in vivo test showed that Pt(IV)-CA4 conjugates exhibited significantly enhanced tumor suppression and reduced acute toxicity (weight loss) in LLC-bearing mice." (PMID 36324675, 2022). "CA-4 selectively inhibits tumor neovascularization, causing rapid vascular shutdown and tumor necrosis." (PMID 34959731, 2021). "The CA4-NPs effectively disrupted established tumor blood vessels, caused extensive tumor necrosis and inhibited tumor growth, but induced severe hypoxic conditions which resulted in the overexpression of PD-L1 in tumor tissues." (PMID 33933077, 2021). "CA-4 causes occlusion of the tumour vasculature, resulting in hypoxia-induced necrosis, which targets the core of solid tumours." (PMID 31947889, 2020). "At low doses, CA-4 stabilizes tumor vasculature and promotes immune infiltration, while at higher doses, it disrupts the vasculature, causing vessel collapse, hemorrhage, and tumor necrosis." (PMID 40140726, 2025). "Nevertheless, CA‐4 has been demonstrated to render chemotherapy unsuccessful because of poor lethality of residual tumor tissue, despite its capability to cause massive tumor cell necrosis." (PMID 40323152, 2025). "CA4 itself has good selectivity for central tumor blood vessels and after being linked with PEG-b-PAsp by ester bond, CA4-NPs could offer significant advantages of EPR effect and acid-sensitive (pH = 5.5) effect to TME." (PMID 33933077, 2021). "Moreover, Chen and coworkers also demonstrated that the expression of matrix metalloproteinase 9 (MMP9, a typical tumor-associated enzyme) in treated tumors (4T1) could be markedly increased by more than 5-fold after treatment with CA4-NPs." (PMID 31754379, 2019). "While the most important clinical feature afforded by CA4 relates to its role in the collapse of blood vessels of cancer tissue, CA4 has also been shown to cause cell death of cancer cells, either directly via apoptosis, or indirectly through tumor autophagy and necrosis." (PMID 30674916, 2019). "In summary, these data suggest that at low dose, both CA-4 and eribulin normalize tumor blood vessels by inducing pericyte differentiation which in turn improves vessel integrity and overall tumor perfusion." (PMID 40140727, 2025). "In this study, we demonstrated in mouse tumor models the selective capacity of low dose CA-4 or eribulin to induce tumor pericyte phenotype switching from a highly proliferative to a contractile state by activating RhoA kinase." (PMID 40140727, 2025). "CA‐4 and ES‐Cu synergistically inhibit tumor growth, induce immune responses, and reverse the immunosuppressive microenvironment, offering an effective multidimensional therapeutic strategy for HCC treatment." (PMID 40323152, 2025). "Microtubule-binding drugs such as CA-4, eribulin, paclitaxel and vinorelbine have all been evaluated for their effects on tumor vasculature." (PMID 40140727, 2025).
tumor (continued). "The in vivo evaluations using the 4T1 xenograft BALB/c mouse model showed that CA4-encapsulated nanoliposomes started proliferating at the tumor site 3 h after injection, with the most significant tumor accumulation at 24 h." (PMID 40006557, 2025). "In particular, CA‐4 suppressed cellular microtubule polymerization, blocked tumor cell mitosis, and induced ROS generation." (PMID 40323152, 2025). "Although the exact mechanism by which CA-4 reduces ROS in stimulated lymphocytes remains to be fully elucidated, the differential effects observed between healthy and tumor cells strongly support the selective antitumor activity of the compound." (PMID 39766242, 2024). "Consistent with our results, other studies have reported that CA-4 has significantly lower cytotoxicity toward healthy cells compared to tumor cells." (PMID 39766242, 2024). "Unlike the conventional chemotherapeutic agents that primarily target the tumor cells, CA-4 disrupts the tumor’s blood vessels, cutting off oxygen and nutrient supply, and leading to rapid necrosis of the central tumor mass." (PMID 39766242, 2024). "CA4 nanomedicines (C-NPs) represent prodrugs of vascular disrupting agents (VDAs) that primarily localize CA4 around blood vessels with certain degrees of tumor vascular targeting." (PMID 38375454, 2024). "CA-4 and its analogues have been shown to exert cytotoxic effects on a range of tumor cells at nanomolar-to-micromolar concentrations, including cells resistant to other antitumor agents." (PMID 39766242, 2024). "CA4-NPs, a vascular disrupting agent, was used to increase the fibrin level within tumors and exacerbate tumor hypoxia." (PMID 38440219, 2024). "CA4-NPs can selectively disrupt tumor blood vessels, leading to hemorrhage and increased hypoxia within the treated tumors." (PMID 38440219, 2024). "This release of CA-4 leads to more extensive and prolonged damage, effectively killing tumor cells that survive the initial PDT." (PMID 39144632, 2024). "CA4 can disrupt blood vessel structure in tumors by binding endothelial cell tubulin and blocking tumor necrosis by inhibiting the exchange of oxygen and other nutrients." (PMID 37102886, 2023). "The combination of CA4-NPs with MMP9-DOX-NPs showed significant antitumor efficacy in situ in 4T1 tumor-bearing mouse models." (PMID 37111692, 2023). "Intriguingly, while enabling disruption of blood supply into the tumor cells, CA4 maintains normal blood flow into adjacent normal tissues." (PMID 36865913, 2023). "As a tumor vascular targeting agent, CA4 can inhibit the expression of vascular endothelial growth factor." (PMID 37176991, 2023). "A study reported that CA4 is a newly identified tumor suppressor gene in CRC by targeting the WTAP–WT1–TBL1 axis through the inhibition of the Wnt signaling pathway." (PMID 36991484, 2023). "Along this line, polymeric NP composed of poly (l-glutamic acid)-CA4 conjugate (PLG-CA4) has been used to enhance CA4 accumulation and retention in tumor tissue." (PMID 37273793, 2023). "CA4 release occurs faster to induce vascular disruption and cut off the tumor nutrient pathway connected to other tissues." (PMID 37273793, 2023). "The results demonstrated the advantages of the CA4 nanodrug conjugate, as it allowed high dissemination and slow release of CA4 focused on tumor blood vessels." (PMID 37273793, 2023). "In the drug-loaded PDA co-delivery nanohybrids (PDA@PLGA/DC NPs), DOX and CA4 synergistically induced tumor cell apoptosis by interfering with DNA replication and inhibiting tumor angiogenesis, respectively." (PMID 37176991, 2023). "When combined with nano-CA4, the hypoxic environment of the tumors accelerated the release of RNase A, leading to inhibition of tumor growth with a tumor suppression rate up to 91.7%." (PMID 35119544, 2022). "Mechanistically, CA4 interacts directly with WTAP, and the tumor suppressor function of CA4 is dependent on WTAP modification." (PMID 36139062, 2022).